PDCD4 (programmed cell death 4)
Diseases named in the same sentence as PDCD4 in open-access papers (continued):
Sharing a sentence is not in itself a finding about the gene and the disease.
lung carcinoma (continued). "Though a positive role for GSK-3β involvement in PDCD4 protein regulation has been recently reported in lung cancer cells, our studies provide the first evidence for transcriptional regulation of PDCD4 by GSK-3β in a developmental neuronal setting." (PMID 24837604, 2014). "For instance, it has been demonstrated that miR-182 acts as an oncogenic miRNA by interacting and negatively regulating PDCD4 in ovarian and lung cancer." (PMID 25115394, 2014). "This interaction between PDCD4 and p62 highlights a potential therapeutic target for enhancing autophagic flux, which could lead to the suppression of lung cancer growth and the induction of cancer cell death." (PMID 38891090, 2024). "Similarly, miR-21 overexpression leads to decreased PDCD4 expression, contributing to radioresistance in lung cancer." (PMID 39408872, 2024). "Both PDCD4 and RUNX3 are tumor suppressor genes, and their co-downregulation may be one of the causes of lung cancer." (PMID 33691643, 2021). "In addition, we also found antagomiR‐21 administration obviously enhanced the expression levels of PTEN and PDCD4 in lung cancer." (PMID 32281297, 2020). "However, the expression levels of PDCD4 were decreased in all lung cancer tissues when compared with normal tissues as determined by florescence immunohistochemistry." (PMID 27323401, 2016). "We determined whether PTEN and PDCD4 were critical targets of miR-21 in primary human lung cancer cells." (PMID 27286259, 2016). "Interestingly, antioxidants such as CAT were able to inhibit chronic Cr(VI)-induced miR-21 elevation and PDCD4 suppression, demonstrating that ROS have a crucial role in the regulation of the miR-21/PDCD4 signaling in lung cancer, which the authors suggested to happen through IL-6/STAT3." (PMID 32575472, 2020). "Tumor suppressor programmed cell death 4 (PDCD4) in lung cancer tissues were positively correlated with the longer overall survival of lung cancer patients with PTX treatment, suggesting that PDCD4 may be used as a predictive marker of resistance to PTX in lung cancer patients." (PMID 28615068, 2017). "For example, miR‐21 is one of the most commonly upregulated miRNAs in lung cancer, acting as an oncomiR by targeting tumor suppressor genes such as PTEN and PDCD4, thereby promoting cancer progression and metastasis." (PMID 39991629, 2025). "Lung adenocarcinoma secreted miR-21 suppresses programmed cell death 4 (PDCD4), promoting the generation of OCs and hence facilitating osteolytic lesions in lung cancer." (PMID 38571500, 2024). "Pulmonary infections of Gram-negative bacteria are common in lung cancer patients and elevated ROS production is critical for LPS to be able to induce miR-21 expression, promoting primary lung cancer outgrowth through miR-21 targeting of PTEN and PDCD4." (PMID 32575472, 2020). "PTEN, PDCD4 or RECK gene was overexpressed in A549 cells, while miR-21-5p was knocked down in MSCs, A549 or H23 lung cancer cells or primary monocytes by miR-21-5p inhibitor transfection." (PMID 30736829, 2019). "According to research, miRNA-183 can restrict PDCD4 expression and hence prevent the apoptosis of transforming growth factor beta 1-induced human hepatocellular carcinoma cells, also miRNA-183 is suggested to restrict FOXO expression in lung cancer." (PMID 37808196, 2023).
lung carcinoma (continued). "It functions as an oncogene through silencing many tumor suppressor genes such as PDCD4, PTEN, SMAD7, HIF-1α, and others, all of which play key roles in different aspects of lung cancer development including cell cycle, apoptosis, drug resistance, and distant metastasis." (PMID 34885115, 2021). "In a cohort of 511 lung cancer patients, a negative correlation between PDCD4 and miR-21-5p was observed." (PMID 34885115, 2021). "Moreover, shH19 combined with Gefitinib treatment obviously increased the protein expression levels of PTEN and PDCD4, while decreased the expression levels of NFIB in lung cancer in vivo." (PMID 32281297, 2020). "Furthermore, the results demonstrated that shH19 administration significantly enhanced the expression levels of PTEN and PDCD4, while decreased the expression levels of NFIB in lung cancer." (PMID 32281297, 2020). "PDCD4 has been demonstrated to induce apoptosis in breast and lung cancer cells In contrast, no apoptotic effect of PDCD4 was observed in other studies." (PMID 22272332, 2012). "Moreover, the fact that some lung cancer cells are characterized by high expression of PDCD4 suggests that this protein is not always tumor suppressive." (PMID 39885142, 2025).
hepatocellular carcinoma (45 papers, 2009 to 2025). A malignant tumor that arises from hepatocytes. "Here, we show that when HBx is ectopically expressed in hepatoma cells, it up-regulated miRNA-21 significantly, which caused inhibition of its target proteins, PDCD4 and PTEN." (PMID 24633222, 2014). "This study examined the effect BCAA has on PDCD4 expression and related cellular pathways in Huh7 hepatoma cells." (PMID 41439995, 2025). "The degradation of PDCD4 protein in the autophagy system was inhibited, and the protein levels were upregulated in Huh7 hepatoma cells." (PMID 41439995, 2025). "We recently reported that PDCD4 knockdown suppressed cell growth by inducing cellular senescence in a p21-dependent manner in human hepatocellular carcinoma (HCC) cells." (PMID 36522523, 2023). "We recently showed that PDCD4 knockdown induced cellular senescence by upregulating the p21 expression and downregulated the cell cycle regulators CDKs in Huh7 hepatoma cells." (PMID 36522523, 2023). "As an example, miR-183-5p is upregulated in hepatocellular cancer to inhibit cancer cell apoptosis by suppressing PDCD4 expression." (PMID 34611229, 2021). "The TPA-activated PKCδ and PKCε signaling pathways phosphorylate PDCD4, leading to its degradation by the proteasome system in Huh7 hepatocellular carcinoma cells." (PMID 31952347, 2020). "We demonstrated for the first time that the tumor suppressor PDCD4 is degraded by the p62-mediated selective macro-autophagy system in Huh7 hepatoma cells." (PMID 31952347, 2020). "We have observed rapamycin inhibited the EGF-induced down-regulation of PDCD4 mRNA levels in Huh7 hepatoma cells." (PMID 31075975, 2019). "TGF-β1 treatment of Huh7 hepatoma cells increased PDCD4 expression up-regulating PDCD4 mRNA expression through the TGF-β1-activated Smad signaling pathway and induced apoptosis." (PMID 31075975, 2019). "CDKNI4 knockdown rescued the senescence and cell death as well as the inhibition of pRb-phosphorylation and CDK expression induced by PDCD4 knockdown in the hepatoma cells." (PMID 31075975, 2019). "It was demonstrated that the expression of PDCD4 increases in cultured Huh7 hepatoma cells exposed to TGF-β1 and that ectopic PDCD4 overexpression induces such cells to undergo apoptosis." (PMID 31075975, 2019). "Morphological changes were observed in the PDCD4 knockdown cells of all the three hepatoma cell lines, and those cells were frequently positive for β-galactosidase staining." (PMID 30687637, 2018). "Next, the expression of p21 (Waf1/Cip1) and p27 (Kip), which are CDK inhibitors, was assayed after the p2 or k603 siRNA-mediated PDCD4 knockdown in these three hepatoma cell lines." (PMID 30687637, 2018). "When hepatoma cells were treated with PDCD4-specific siRNAs, the cells showed enlarged and flattened morphological changes that are usually observed in senescent cells." (PMID 30687637, 2018). "Previous studies from our group have shown that the PDCD4 over-expression induced by TGF-β1 led to hepatoma cell apoptosis." (PMID 30687637, 2018). "In this study, miR-590-3p was reported to be upregulated in hepatocellular carcinoma, and promoted carcinogenesis by inhibiting tumor suppressor gene PDCD4 and PTEN." (PMID 28423728, 2017). "MHCC97-H and MHCC97-L cells served as control groups, and osteopontin (OPN), TGFβ-1, and programmed cell death protein 4 (PDCD4) gene expression levels in hepatoma cells was set as 100 %." (PMID 26003220, 2015).
hepatocellular carcinoma (continued). "TGFβ-1, osteopontin (OPN), and programmed cell death protein 4 (PDCD4) genes expression of hepatoma cells were detected by quantitative real-time polymerase chain reaction (qPCR) before and after co-cultured experiments." (PMID 26003220, 2015). "Apoptosis in hepatocellular carcinoma cells was induced by PDCD4 through mitochondrial events and the caspase cascade, including increases in cytosolic cytochrome c and mitochondrial Bax and a reduction in procaspase-3, -8, and -9." (PMID 24348845, 2014). "For instance, lncRNA XIST could regulate the progression of hepatocellular carcinoma via targeting miR-497-5p to regulate the expression of PDCD4." (PMID 33663502, 2021). "For example, SNHG1 soaks up miR-195-5p to regulate PDCD4 expression in hepatocellular carcinoma." (PMID 32497022, 2020). "They demonstrated that miR-21 promotes the migration and invasion processes in hepatocellular carcinoma cells through the miR-21/PDCD4/AP-1 feedback loop, which may represents a therapeutic target in this malignancy." (PMID 31427899, 2019). "The results indicate that TGF-β1 may induce apoptosis via PDCD4 overexpression in the Huh 7 hepatoma cells." (PMID 31075975, 2019). "A previous study has shown PDCD4 might be a target gene of miR-183 in human hepatocellular carcinoma cells." (PMID 31210063, 2019). "In this study, we showed that siRNA-mediated PDCD4 knockdown induced the suppression of cell growth by inhibiting the phosphorylation of retinoblastoma protein (Rb) by down-regulating Rb and CDKs, which phosphorylate Rb in hepatoma cell lines." (PMID 30687637, 2018). "Our results indicate that PDCD4 plays important roles in cell cycle regulation and the induction of cellular senescence in human hepatoma cells and may be a potential target in antineoplastic therapies." (PMID 30687637, 2018). "Our data showed that PDCD4 knockdown increased the number of β-galactosidase-positive cells, up-regulated the p21 levels and down-regulated the CDKs expression, supporting the induction of cellular senescence in hepatoma cells after PDCD4 knockdown." (PMID 30687637, 2018). "The results indicated that PDCD4 knockdown suppressed hepatoma cell growth." (PMID 30687637, 2018). "These phenomena indicated that the hepatoma cells with PDCD4 knockdown might be undergoing differentiation or cellular senescence." (PMID 30687637, 2018). "Furthermore, the FACS analysis revealed that there was no accumulation of cells in any specific cell cycle phase, except for an increase in the pre-G1 cell population, among the PDCD4 knockdown hepatoma cells." (PMID 30687637, 2018). "Also, lncRNAGAS5 acted as a tumor suppressor in hepatocellular carcinoma through negative regulation of miR-21 to up-regulate its targets programmed cell death 4 (PDCD4) and phosphatase and tensin homologue (PTEN), resulting in inhibition of cancer cell migration and invasion." (PMID 29440672, 2018). "Thus, PDCD4 is an important cell cycle regulator of hepatoma cells and may be a promising therapeutic target for the treatment of hepatocellular carcinoma." (PMID 30687637, 2018). "To determine the effects of PDCD4 knockdown on cell cycle regulators in hepatoma cells, we investigated the expression of retinoblastoma protein (Rb), phospho-Rb (p-Rb) and its controller cyclin-dependent kinases (CDKs) by Western blotting of the p2 and k603 PDCD4-specific siRNAs-treated cells." (PMID 30687637, 2018). "To elucidate the effect of PDCD4 knockdown on the cell cycle in hepatoma cells and gain further insights into PDCD4 function, we treated cells with PDCD4-specific siRNAs and investigated the expression of factors involved in cell cycle control in hepatoma cells." (PMID 30687637, 2018). "When investigating the BCAA effect on the Huh7 hepatoma cell growth, BCAA was found for the first time to upregulate PDCD4 protein levels in the cells." (PMID 41439995, 2025).
hepatocellular carcinoma (continued). "In hepatocellular carcinoma, LINC00472 has been found to suppress tumor growth through the miR-93-5p/PDCD4 pathway." (PMID 35258410, 2022). "Overexpression of miR-21 can regulate the expression of invasion- and metastasis-related target genes in the hepatocellular carcinoma (HCC) cell line HepG2 and the lung cancer cell line A549 by inhibiting the expression of programmed cell death 4 and PTEN, which are involved in apoptosis." (PMID 34485600, 2021). "In human hepatocellular carcinoma (HCC), the downregulation of PDCD4 by miR-93 (NCBI GeneID: 407050) promotes HCC cell migration and invasion via the epithelial-mesenchymal transition (EMT) pathway." (PMID 31620370, 2019). "Intriguingly in another study, miRNA-590-3p is found upregulated in hepatocellular carcinoma (HCC), accelerating tumorigenic process via targeting tumor suppressor gene PDCD4 and PTEN." (PMID 29246025, 2017). "TGF-β induced miR-21 expression in fibroblasts and mir-183 downregulated PDCD4 and inhibited TGF-β–induced apoptosis in human hepatocellular carcinoma cells." (PMID 25144746, 2014). "PDCD4 was suggested to be a proapoptotic molecule involved in transforming growth factor beta-1 (TGF beta-1) induced apoptosis in hepatocellular carcinoma (HCC)." (PMID 22272332, 2012). "Expression of Pdcd4 was found to be reduced in hepatocellular carcinoma (HCC)." (PMID 19728867, 2009). "Furthermore, this study aimed to assess the impact of BCAA on the proliferation of Huh7 hepatoma cells, thereby elucidating the relationship between BCAA-induced PDCD4 regulation and cellular behavior." (PMID 41439995, 2025). "Though knockdown of p62/SQSTM1 (sequestosome-1) led to the upregulation of PDCD4 in hepatoma cells, we found that p62 silencing had no regulatory effects on PDCD4 expression in NSCLC cells." (PMID 39885142, 2025). "The results indicate that PDCD4 is an important cell cycle regulator and may contribute to the control of cell cycle via p21(CDKNI4) in hepatoma cells." (PMID 31075975, 2019). "The mTOR inhibitor rapamycin does not inhibit the TPA-induced PDCD4 suppression in Huh7 hepatoma cells." (PMID 31075975, 2019). "Further, from the TGFβ-1 and PDCD4 gene expression by qPCR method, test results showed hMSC promoted hepatoma cells proliferation but had no obvious effect on hepatoma cells apoptosis." (PMID 26003220, 2015). "Since PDCD4 and PTEN are pro-apoptotic proteins, our data is in agreement with the previous data that HBx inhibits apoptosis and enhances cellular proliferation in hepatoma cells." (PMID 24633222, 2014). "In hepatocellular carcinoma (HCC), for instance, miR-21 is significantly upregulated, promoting HCC cell proliferation, migration, and chemoresistance by suppressing tumor suppressor genes like PTEN and PDCD4." (PMID 40277513, 2025).
glioma (41 papers, 2010 to 2025). A benign or malignant brain and spinal cord tumor that arises from glial cells (astrocytes, oligodendrocytes, ependymal cells). "The loss of expression of PDCD4 is diagnostic indicator for different human cancers, and is prognostic indicator for survival in cancers of the breast, liver, colon, lung, glioma, and esophagus." (PMID 33304903, 2020). "PDCD4 as a diagnostic for human cancer staging and prognostic for survival in colon, lung, liver, breast, glioma and esophageal cancers has been reported earlier." (PMID 25991676, 2016). "While PDCD4 is reported to be less expressed in glioma, the underlying mechanism remained unclear." (PMID 33304903, 2020). "In gliomas, hsa-miR-21-5p downregulates PDCD4 and TIMP3, facilitating tumor growth and resistance to apoptosis, making it a marker of poor prognosis." (PMID 40362695, 2025). "Further studies indicated that the tumorigenic actions of HOTAIR in gliomas additionally rely on its ability to suppress programmed cell death protein 4 (PDCD4) in a PRC2-dependent manner." (PMID 38366205, 2024). "FAT1 has shown oncogenic effect in glioma by down-regulating the tumour suppressor gene PDCD4, which leads to activation of AP1 Transcriptional activity thereby increasing the EMT and inflammatory microenvironment of tumour Cells." (PMID 37476290, 2023). "The expression level of circulating miR-155 correlated positively with oncogene PDCD4 (p < 0.0001, r = 0.753) in plasma samples of high-grade glioma patients." (PMID 35646622, 2022). "As result, the current study showed that circulating miR-155 correlated positively with PDCD4 in plasma of high-grade glioma patients." (PMID 35646622, 2022). "Expression of miRNA-21 was increased and anti-tumorigenic genes (FoxO1, PTEN, and PDCD4) were decreased in exosomes within T. gondii-infected U87 glioma cells." (PMID 36180486, 2022). "The deletion of Fat1 signaling reduce glioma cells migration and invasiveness, an effect that was related to an increase of the expression of tumor-suppressor gene programmed cell death 4 (PDCD4)." (PMID 35269788, 2022). "In gliomas, miR-21 can inhibit the expression of PDCD4, thus inhibit the apoptosis of glioma cells and promote cell proliferation and invasion." (PMID 34775378, 2021). "Our data indicate the potential clinical value of treatment with VEGF or STAT3 inhibitors in glioma patients expressing low levels of PDCD4." (PMID 33304903, 2020). "The analysis indicated PDCD4 to be significantly down-regulated in seven glioma cell lines than in normal astrocytes, consistent with previous studies." (PMID 33304903, 2020). "Taken together, our data suggests PDCD4 to be down-regulated in glioma cells and acts as a tumor suppressor." (PMID 33304903, 2020). "At the same time, siRNA carried by SPIONs can efficiently inhibit the expression of the target gene HOTAIR and remove its inhibition against PDCD4 transcription, thereby reducing glioma proliferation and invasion." (PMID 32174801, 2020). "The major mediator of tumor angiogenesis is VEGF, whose expression was found to be reduced upon over-expression of PDCD4 in the glioma cells." (PMID 33304903, 2020). "In this study, we observed that the mRNA and protein levels of PDCD4 were significantly down-regulated in a panel of well-characterized human glioma cell lines, consistent with the TCGA data analysis." (PMID 33304903, 2020). "In this study, we showed that PDCD4 is down-regulated in glioma cells and acts as a tumor suppressor." (PMID 33304903, 2020). "Consistent with our findings for anchorage-independent growth, the over-expression of PDCD4 significantly suppressed the tumorigenic potential of glioma cells and prolonged the survival of tumor-bearing mice." (PMID 33304903, 2020). "Next, we tested the mRNA and protein levels of PDCD4 in a panel of well-characterized human glioma cell lines and normal astrocytes." (PMID 33304903, 2020).